LBR (lamin B receptor)
Diseases named in the same sentence as LBR in open-access papers (continued):
Sharing a sentence is not in itself a finding about the gene and the disease.
liver fibrosis (1 paper, 2022). "Presence of anti-LBR does not correlate with patients’ survival rate, but is connected with liver fibrosis." (PMID 35453551, 2022).
prostate carcinoma (1 paper, 2022). A carcinoma that arises from epithelial cells of the prostate gland. "Studies have shown that TMEM147 interacts with the lamin B receptor in the endoplasmic reticulum, affecting the expression level and localization of the receptor, and TMEM147 can also promote the proliferation of prostate cancer." (PMID 37305349, 2022).
tauopathy (1 paper, 2026). Neurodegenerative disorders involving deposition of abnormal tau protein isoforms (tau proteins) in neurons and glial cells in the brain. "Using the tauopathy mouse model (P301S PS19), we demonstrate that oligomeric tau (oTau) directly binds to the Lamin B Receptor (LBR), inducing nuclear envelope invaginations as revealed by electron microscopy." (PMID 42017968, 2026).
cancer (15 papers, 2017 to 2026). A tumor composed of atypical neoplastic, often pleomorphic cells that invade other tissues. "The lamin B1 receptor (LBR) is also lost when DNA is damaged by ɣ-radiation in cancer cells, which causes changes in chromatin structure including blebbing, micronuclei, and CCFs and promotes senescence in cancer cells." (PMID 33755107, 2022). "We recently found that DNA damage induced by γ-irradiation or replication stress (RS) in cancer cells leads to downregulation of the lamin B receptor (LBR) and lamin B1 (LB1) associated with changes in nuclear morphology." (PMID 32316379, 2020). "As we could demonstrate the deregulation of LMNB1 in MM, its influence on gene expression and, thus, its relevance in cancer-associated biological processes, we aimed to further investigate if these effects are also modulated by the lamin B receptor (LBR)." (PMID 35883595, 2022). "Similarly, miR-483-3p that targets Lamin-B receptor (LBR) and has been associated with cancer progression, is assessed as a potential marker due to substantial upregulation in the plasma of AD patients as compared to normal controls that provide a new approach to the clinical diagnosis of AE." (PMID 33178551, 2020). "For this study, we used two cancer cells lines of different histological origin, both wild-type and shRNA knockout targeting LBR." (PMID 32316379, 2020). "Manipulation of either miR-222 expression or LBR function provide candidate approaches for development of these types of anti-cancer therapies." (PMID 31481734, 2019). "Our functional experiments in cancer cell lines show that heterochromatin in cancer cells is tethered to the INM by LBR, which is downregulated together with lamin B1 at the onset of cell transition to senescence." (PMID 29415520, 2018). "However, owing to the loss of the principal tether protein LBR/LB1 in the beginning of cancer cell senescence, we can speculate that the other heterochromatic loci containing LADs that are specifically recognized by LBR were also detached from the lamina and unfolded." (PMID 29415520, 2018). "identify a key player in nuclear fragility in confined cancer cell migration: the Lamin B receptor." (PMID 42252781, 2026). "LBR is one of the most important proteins in the inner nuclear membrane and is known to play critical roles in tethering heterochromatin to nuclear periphery during development and in cancer cells." (PMID 37223461, 2023). "To further explore the apparent coordinated behavior of both proteins in cellular processes we performed experiments: (i) To confirm the capacity of LBR to attach heterochromatin (HC) to the INM in cycling cancer cells and to detach it from the INM after downregulation in senescence." (PMID 29415520, 2018). "LBR also tethers heterochromatin to the INM in cycling cancer cells." (PMID 28858257, 2017). "We were interested in whether the ssDNA induced at stalled replication foci by this treatment would result in cell death or the transition of the cells to senescence and whether this senescence would be accompanied by the loss of LBR and LB1 that we observed after γ‐irradiation of cancer cells." (PMID 30982228, 2019). "Of note, It was revealed that the expression of most genes was generally consistent with results of TCGA cancer set, such as TRIM24, HMG20B, CBX6, IDH1, RCC1, RYBP, CBX7, and LBR." (PMID 36246611, 2022). "This phenotype was observed not only in senescent cells but also in cells treated with LBR‐specific shRNA, indicating that LBR tethers heterochromatin to INM in cancer cells and LB1 is an integral part of this anchoring." (PMID 30982228, 2019). "Our results show downregulation of both LBR and LB1 at the onset of senescence induced by γ-irradiation in two cancer cell lines (MCF7 and U2OS)." (PMID 29415520, 2018). "LBR is one of the most important proteins of the INM, mediating the peripheral tethering of heterochromatin at early developmental stages and in cycling cancer cells." (PMID 28858257, 2017).
cancer (continued). "In particular, our data demonstrate that reduced expression of miR-222 or overexpression of LBR in CAFs greatly reduces their ability to promote aggressive behaviours in cancer cells, supporting the proposal that CAF phenotypes are not fixed and could be normalised therapeutically." (PMID 31481734, 2019).
skeletal dysplasia (8 papers, 2016 to 2025). Any Mendelian diseases that affects growth and development of the skeleton. "Complete loss of function due to bi-allelic LBR variants causes the severe Greenberg skeletal dysplasia, a lethal chondrodystrophy characterized by fetal hydrops, short limbs, and abnormal chondro-osseus calcification." (PMID 37347778, 2023). "Human PHA is caused by heterozygous loss of function variants in the LBR gene encoding lamin receptor B. Bi-allelic LBR loss of function causes Greenberg skeletal dysplasia which results in fetal lethality." (PMID 37347778, 2023). "It has been reported that one heterozygous variant c.1757G>A in the LBR gene was detected in a patient with bilobed neutrophil nuclei and a mild skeletal dysplasia phenotype; another heterozygous variation in the LBR gene was detected in the trans position." (PMID 36712868, 2022). "The two point mutations, LBR N547D and LBR R583Q, are both associated with Greenberg skeletal dysplasia when both LBR alleles are mutated." (PMID 27336722, 2016). "However, patients with homozygous/compound heterozygous mutations in LBR can lead to severe perinatal fatal autosomal recessive skeletal dysplasia, Greenberg skeletal dysplasia, and even those who survive are accompanied by severe skeletal dysplasia." (PMID 40980134, 2025). "This very mild skeletal dysplasia was caused by a double heterozygous mutation in the LBR gene." (PMID 28854936, 2017). "LBR mutations have been implicated in two congenital disorders: Pelger–Huët anomaly, where a single mutation in one LBR allele causes hypolobulated granulocyte nuclei and Greenberg skeletal dysplasia, which is a recessive, perinatally lethal, bone development disease." (PMID 33076344, 2020). "Interestingly, mounting evidence indicates that Greenberg skeletal dysplasia results from the inheritance of two mutant LBR alleles that when heterozygous cause Pelger-Huët anomaly, indicating that the two diseases represent different allelic states of the same chromosomal lesion." (PMID 27336722, 2016). "Having demonstrated that LBR is essential for cell viability under cholesterol-depleted conditions, we asked whether the mutant variants of LBR found in Pelger-Huët anomaly and Greenberg skeletal dysplasia can sustain cholesterol biogenesis in human cells." (PMID 27336722, 2016). "Mutations in the lamin B receptor (LBR) gene cause a phenotypic spectrum ranging from isolated PHA, PHA with mild skeletal abnormalities, to the embryonic-lethal Greenberg skeletal dysplasia." (PMID 40980134, 2025). "In this study, two fetuses with moderate skeletal dysplasia with homozygous variation c.1757G>A of the LBR gene were studied to expand the phenotypic spectrum and further guide the prenatal diagnosis of this disease." (PMID 36712868, 2022). "Intensive analysis on bioinformatics and familial co-segregation suggest that the homozygous variation in the LBR gene is responsible for this recurrent prenatal moderate skeletal dysplasia." (PMID 36712868, 2022). "This mutation results in a C-terminally truncated LBR protein that is missing the final three membrane spanning helices that form the sterol-reductase domain of LBR and results in Greenberg skeletal dysplasia in homozygous individuals." (PMID 27336722, 2016). "Another unexpected outcome of this study is that C-terminally truncated LBR proteins found in both Pelger-Huët anomaly and Greenberg skeletal dysplasia are rapidly degraded by a proteasome-dependent protein quality-control pathway that appears to be distinct from the canonical ERAD pathway." (PMID 27336722, 2016). "The lamin B receptor (LBR) gene is located in chromosome 1q42.12 and encodes the lamin B receptor, an intracellular protein that binds to lamin B. LBR mutations are associated with a broad phenotypic spectrum ranging from non-lethal to lethal skeletal dysplasias." (PMID 36712868, 2022).
skeletal dysplasia (continued). "However, LBR mutations that abolish sterol reductase activity could cause Greenberg skeletal dysplasia without Pelger-Huët anomaly." (PMID 28854936, 2017). "Genetic variation in LBR affects the expression of LBR protein, which in turn correlates with a continuum of clinical manifestations ranging from no phenotype to isolated PHA through PHA with mild skeletal dysplasia to Greenberg skeletal dysplasia." (PMID 40980134, 2025).
tumor (8 papers, 2019 to 2026). "The predicted upregulation of RPLs due to LBR knockdown indicates a tumor suppressive release regarding senescence and reduced proliferation." (PMID 35883595, 2022). "Taken together, these results suggest that miR-222 upregulation, and subsequent LBR downregulation, within fibroblasts in the tumour microenvironment contribute to progression of BC, through induction of proliferation and EMT-related motility." (PMID 31481734, 2019). "LBR expression was relatively reduced in tumour stroma, in contrast to ACTA2 (smooth muscle actin), which was relatively high in tumour stroma." (PMID 31481734, 2019). "In one approach, we examined whether breast normal stroma or tumour stroma exhibit differential expression of LBR using immunohistochemistry." (PMID 31481734, 2019). "In the Th17 lineage, RORC (receptor) is upregulated on the tumor infiltrating CD4+ T-cells and its ligands (CYP51A1, FDFT1, HSD17B7, LBR, TM7SF2, MSMO1, NSDHL) are also upregulated on the tumor cells, implying GBM expresses ligands that induces Th17 phenotype in tumor infiltrating helper T-cell." (PMID 34012510, 2021).
infection (3 papers, 2019 to 2023). The state of being infected such as from the introduction of a foreign agent such as serum, vaccine, antigenic substance or organism. "In contrast, the eight LbR strains caused a slight infection; they produced small lesions on cotyledons and stems." (PMID 38132768, 2023). "Three LbR strains (P5, P6, P7) showed a moderately suppressive effect on infection by Lb20; the effect depended on the proportion of their pycnidiospores with Lb20 in the mixed inoculum." (PMID 38132768, 2023). "The cultural filtrates (CFs) of the eight LbR strains differed in efficacy in the suppression of infection by L. biglobosa Lb20 on rapeseed leaves." (PMID 38132768, 2023). "The eight LbR strains showed different effects on infection by L. biglobosa Lb20." (PMID 38132768, 2023). "First, SinC is found to localize to the inner nuclear membrane during the late stages of infection where it interacts with the nucleoporin ELYS, lamin B1, LEM (LAP2, emerin, MAN1) domain proteins, lamin-associated polypeptide 1 (LAM1), and lamin B receptor (LBR)." (PMID 33476322, 2021). "However, in the treatments with the CF of seven LbR strains (P1, P2, P3, P5, P6, P7, P8), no visible infection or reduced infection was observed." (PMID 38132768, 2023). "The LbR strain P8 had no detectable suppressive effect (<10%) on infection by L. biglobosa." (PMID 38132768, 2023).
metabolic disorder (1 paper, 2018). "Although these findings are highly significant and imply that GRBGD is in fact a metabolic disorder of cholesterol biosynthesis, the pathogenesis of developmental anomalies in LBR-associated diseases remains unknown." (PMID 30518689, 2018).
skeletal diseases (1 paper, 2018). "As chondrogenesis and ossification critically depend on the synthesis of numerous highly glycosylated proteins, such as the extracellular matrix (ECM) proteoglycans, our findings likely represent the shared pathogenic basis of skeletal diseases caused by LBR or GMAP-210 deficiency." (PMID 30518689, 2018).
LBR also shares sentences with these, for which no sentence is quoted: genetic disorders (2 papers); leukemia (2); lupus (2); adenocarcinoma (1); alopecia (1); bone development disease (1); collagen vascular disease (1); cystic fibrosis (1); Hydrocephalus (1); Intellectual disability (1); kidney cancer (1); lung carcinoma (1); lymphoma (1); malnutrition (1); metastatic melanoma (1); non-small cell lung carcinoma (1); osteosarcoma (1); renal fibrosis (1); restrictive dermopathy (1); scoliosis (1); systemic sclerosis (1); Werner syndrome (1).